PVT1 (Pvt1 oncogene)
Diseases named in the same sentence as PVT1 in open-access papers (continued):
Sharing a sentence is not in itself a finding about the gene and the disease.
multiple myeloma (14 papers, 2008 to 2025). "Plasmacytoma Variant Translocation 1 (PVT1), a lncRNA, is located adjacent to the gene MYC, which has been linked to multiple myeloma (MM)." (PMID 32992461, 2020). "Depletion of PVT1 is evidenced to promote cell apoptosis in multiple myeloma." (PMID 34521353, 2021). "These include the DLGAP-1-AS1/miR-26a-5p axis in GC and the PVT1/miR-203a axis in multiple myeloma." (PMID 33080572, 2020). "MYC translocation breakpoints and CNA overlapped several regions of chromatin accessibility in myeloma cell lines that coincide with known enhancers as well as insulator elements that delineate MYC and PVT1 promoter-enhancer interactions." (PMID 31015454, 2019). "Of note, none of the stable myeloma precursor condition cases had any SVs involving the MYC/PVT1 hotspot in sharp contrast with 35% (6/17) in progressive precursor condition cases and 32/80 (40%) MM (Fisher’s exact test p = 0.03 and p = 0.003, respectively)." (PMID 33767199, 2021). "In multiple myeloma, 16% of patients have the PVT1 region rearranged, but independent of the immunoglobulin loci." (PMID 18194563, 2008). "On the other hand, the multiple myeloma cases with translocations in the PVT1 locus without immunoglobulin gene translocation would argue for this locus to be oncogenic in its own right, as do the retroviral integrations into this locus." (PMID 18194563, 2008).
Sepsis (14 papers, 2020 to 2025). Sepsis is defined as life-threatening organ dysfunction caused by a dysregulated host response to infection. "In sepsis patients, the levels of long noncoding RNA plasmacytoma variant translocation 1 (PVT1) are elevated, showing an increase of more than two-fold compared to the healthy control group." (PMID 38473915, 2024). "Plasmacytoma variant translocation 1 (PVT1) silencing was reported to ameliorate inflammation in macrophage during sepsis via downregulating p38/MAPK pathway." (PMID 34630395, 2021). "Previous studies and those of our lab have demonstrated that the lncRNA Pvt1 is involved in cardiac injury after sepsis, but the associated mechanisms are largely unknown." (PMID 38094756, 2023). "Another example is the lncRNA plasmacytoma variant translocation 1 (PVT1), which exhibits elevated expression in myocardial tissue and heart-infiltrating macrophages of sepsis mice." (PMID 38170281, 2024). "In murine model of lipopolysaccharide (LPS)-induced myocarditis, the knockdown of PVT1 prevents the polarization of macrophages toward a pro-inflammatory phenotype, which leads to relieved sepsis-induced myocardial injury." (PMID 38170281, 2024). "Increasing evidence suggests that LncRNAs can be used as potential diagnostic and prognostic biomarkers of ARDS in sepsis, such as MALAT1 and PVT1." (PMID 38238652, 2024). "PVT1 was upregulated in the myocardial tissues of sepsis rats, activated the MAPK/NF-κB pathway, and thus inhibited cardiac function and promoted the secretion of inflammatory factors." (PMID 34775377, 2021). "Additionally, PVT1 levels rise in myocardial tissues and heart-infiltrating macrophages during sepsis-induced myocardial injury." (PMID 38473915, 2024). "In particular, the inhibition of p38/MAPK signaling could also significantly reduce the elevation of PVT1 in sepsis." (PMID 34630395, 2021). "Further, several recent studies have also confirmed that lncRNAs are involved in important regulatory functions in sepsis-induced organ dysfunctions; lncRNA PVT1 plays an important role in sepsis-induced heart dysfunction by regulating cell apoptosis in cardiomyocytes." (PMID 34055659, 2021). "Notably, the knockdown of PVT1 has been shown to alleviate sepsis-induced acute kidney injury." (PMID 40657645, 2025). "PVT1 knockdown could induce apoptosis in lipopolysaccharide-induced H9c2 cells, through up-regulating Bax and caspase-3 and down-regulating Bcl-2, thereby exerting functional roles in sepsis-induced myocardial depression." (PMID 34775377, 2021). "Mechanistically, PVT1 functions as a sponge for miR-20a-5p, which directly targets NLRP3, suggesting that PVT1 promotes cellular juxtaposition through the miR-20a-5p/NLRP3 signaling pathway, thereby exacerbating sepsis-induced AKI." (PMID 40657645, 2025). "Curcumin attenuated the activation of the JNK/NF-κB signaling pathway by inhibiting lncRNA PVT1, thereby alleviating the inflammatory response in AKI in sepsis." (PMID 36429069, 2022). "For example, lncRNA PVT1 induces an increase in TNF-α, IL-6, and IL-1β release, and promotes inflammation by regulating TNF-α and JNK/NF-κB signaling pathways in sepsis." (PMID 34666672, 2021). "In addition, the expression of lncRNA PVT1 was significantly elevated in the cells and tissues of LPS-induced AKI in sepsis." (PMID 36429069, 2022).
acute promyelocytic leukemia (13 papers, 2015 to 2024). An aggressive form of acute myeloid leukemia (AML), characterized by arrest of leukocyte differentiation at the promyelocyte stage, due to a specific chromosomal translocation t(15;17) in myeloid cells. "For instance, PVT1 was proposed as diagnostic and prognostic marker in primary acute promyelocytic leukemia (APL)." (PMID 31003545, 2019). "The findings showed that lncRNA PVT1 contributes to the progression or development of acute promyelocytic leukemia." (PMID 38994720, 2024). "The upregulation of PVT1 contributes to the pathophysiology of different cancers to touch upon ovarian, breast, prostate, mesothelioma, and acute promyelocytic leukemia." (PMID 38994720, 2024). "An early study manifests that the overexpression of PVT1 is related to the proliferation of leukemic cells in acute promyelocytic leukemia (APL)." (PMID 35152842, 2022). "A unique lncRNA, PVT1, has been involved in acute promyelocytic leukemia (APL) through promoting cell proliferation by MYC." (PMID 30466456, 2018). "Amplification of the PVT1 gene contributes to the pathophysiology of several cancers, including ovarian and breast, prostate, mesothelioma and acute promyelocytic leukemia." (PMID 28704924, 2017). "A similar control of MYC protein level by PVT1 was observed also in acute promyelocytic leukemia cells upon PVT1 knock-down." (PMID 28704924, 2017). "A similar mechanism was also documented in acute promyelocytic leukemia cells upon PVT1 knockdown." (PMID 38994720, 2024). "Knockdown MYC in human promyelocytic leukemia cells resulted in down-regulation of PVT1 supporting our analysis that MYC could bind to the putative promoter of PVT1." (PMID 34940755, 2021). "However, different groups agreed on the increased PVT1 level in acute promyelocytic leukemia (APL), compared with mononuclear cells or granulocytes from healthy donors." (PMID 32228602, 2020). "Of note, the over-expression of PVT1 was reported in a wide range of cancers, including breast, gastric, non-small cell lung cancers (NSCLC), pancreatic and hepatocellular carcinomas, and acute promyelocytic leukemia (APL), and serves as a predictor of tumor progression and prognosis." (PMID 33142861, 2020).
clear cell renal cell carcinoma (13 papers, 2017 to 2022). "Among all cancer types, renal clear cell carcinoma displays the strongest upregulation of PVT1, and its misregulation in ccRCC is largely associated with promoter hypomethylation." (PMID 32368310, 2020). "Long non-coding RNA plasmacytoma variant translocation 1 (PVT1) is up-regulated in various human cancers, and our results indicated that PVT1 was up-regulated in clear cell renal cell carcinoma tissues." (PMID 29254209, 2017). "In Clear Cell Renal Cell Carcinoma (ccRCC) a PVT1/HIF2a positive feedback loop has been demonstrated, whereby PVT1 stabilizes HIF2a bound to the enhancer to transactivate its expression." (PMID 35788171, 2022). "The Cancer Genome Atlas cohort analysis revealed that in clear cell renal cell carcinoma, higher PVT1 expression correlated with advanced TNM stage, histological grade, and poor survival." (PMID 29254209, 2017). "PVT1 may thus serve as a novel biomarker, and the PVT1/Mcl-1 pathway may be a useful therapeutic target for clear cell renal cell carcinoma." (PMID 29254209, 2017). "A lncRNA panel including lncRNA-LET, PVT1, PANDAR, PTENP1, and linc00963, were identified to distinguish clear cell renal cell carcinoma from healthy controls." (PMID 29029437, 2017).
glioblastoma (13 papers, 2014 to 2026). The most malignant astrocytic tumor (WHO grade IV). "Using this strategy, 29 essential ER lncRNAs were prioritized, of which 7 were reported to be associated with immune regulation and glioblastoma therapy from previous studies (i.e. PVT1, MIR155HG, and LINC00346)." (PMID 37056564, 2023). "PVT1, on the other hand, has been shown to be upregulated in the brain in several pathological conditions, including ischemic stroke and glioblastoma." (PMID 41602168, 2026). "Recent in vitro and in vivo studies have demonstrated that PVT1 promotes glioblastoma cell proliferation, invasion, and tumor growth in mice while inhibiting apoptosis." (PMID 39015773, 2024). "This study aimed to investigate the role of plasmacytoma variant translocation 1 (PVT1), a long non‐coding RNA, in glioblastoma multiforme (GBM) and its impact on the tumor microenvironment (TME)." (PMID 38287522, 2024). "On the contrary, the mutation of PTEN, EGFR, TTN, NF1, SPTA1 and RB1, which occurred frequently in glioblastoma, were more frequently in PVT1 higher group." (PMID 37202742, 2023). "In glioblastoma, advanced tumor grade correlates with high expression of both PVT1 and the MEF2C gene." (PMID 31249809, 2019). "PVT1 is upregulated in glioblastoma cells, tissues, and GSCs." (PMID 39015773, 2024). "However, silencing PVT1 using CRISPR interference (CRISPRi) technology unexpectedly enhanced cell proliferation of glioblastoma cells and induced pluripotent stem cells." (PMID 32194627, 2020). "In addition, PVT1 regulates E74-like factor 4 (ELF4) expression by competitively binding to miR-365 and controls the stemness of GSCs via the miR-365/ELF4/SOX2 axis Thus, PVT1 may serve as a potential therapeutic target and prognostic indicator in glioblastoma." (PMID 39015773, 2024). "We applied the classification criterion to describe the expression of PVT1, CYTOR, HAR1A and MIAT in glioblastoma subtypes." (PMID 29108264, 2017). "Furthermore, the competition for enhancers between the PVT1 and MYC promoters is proposed to control cell development in glioblastoma cells and induced pluripotent stem cells independent of the PVT1 linear lncRNA." (PMID 32194627, 2020). "High expressions of PVT1 and SNHG18 in glioblastoma samples as opposed to LGG was validated in the previous study." (PMID 34950662, 2021).
osteoarthritis (13 papers, 2018 to 2025). A noninflammatory degenerative joint disease occurring chiefly in older persons, characterized by degeneration of the articular cartilage, hypertrophy of bone at the margins and changes in the synovial membrane. "Long non-coding RNA plasmacytoma variant translocation 1 (PVT1) plays a pivotal role in intercellular communication and has been implicated in the progression of osteoarthritis." (PMID 40636390, 2025). "Previous reports have illustrated that PVT1 exhibits a pivotal role in multiple diseases, such as osteoarthritis, epilepsy and peripheral nerve injury." (PMID 37817266, 2023). "For example, Meng et al21 reported that overexpression of PVT1 aggravates the LPS-induced osteoarthritis inflammation by regulating the HMGB1/TLR4 axis and NF-κB pathway." (PMID 35723715, 2022). "Long non-coding RNA (lncRNA) plasmacytoma variant translocation 1 (PVT1) and growth arrest specific 5 (GAS5) have opposite functions in the apoptosis of chondrocytes, which are involved in the pathogenesis of osteoarthritis (OA)." (PMID 35706414, 2022). "LncRNA PVT1 was identified to modulate chondrocyte apoptosis in osteoarthritis by decreasing miR-488-3p expression." (PMID 32242897, 2020). "Most importantly, previous literature has highlighted that the upregulation of PVT1 promotes chondrocyte apoptosis in osteoarthritis, emphasizing the potential role of PVT1 in RA." (PMID 31303891, 2019). "Studies have previously highlighted the potential of PVT1 as a therapeutic target for osteoarthritis with reports linking the upregulation of PVT1 and the distinct stimulation of chondrocyte apoptosis by sponging to microRNA-488-3p." (PMID 31303891, 2019). "In the present study, we detected the expression of PVT1 in OA tissues and IL-1β-stimulated osteoarthritis chondrocytes." (PMID 30126849, 2018). "Elevated levels of PVT1 in osteoarthritis have been shown to promote chondrocyte apoptosis." (PMID 40493320, 2025). "Taken together, PVT1 participates in the development and progression of osteoarthritis." (PMID 37779916, 2023). "Additionally, PVT1 promotes the production of inflammatory cytokines to aggravate the progression of IL-1β-stimulated osteoarthritis." (PMID 31304055, 2019). "Therefore, this research elucidates how PVT1 aggravates the development of OA, supporting a promising therapeutic agent against degenerative joint diseases including OA." (PMID 30126849, 2018). "It was subsequently demonstrated that exosome-mediated PVT1 targets miR-93-5p, modulates the activity of the HMGB1/TLR4/NF-κB pathway, and influences the progression of lipopolysaccharide-induced osteoarthritis." (PMID 40636390, 2025). "Recently, PVT1 regulated miR-497/AKT3 pathway and influenced the function of osteoarthritis cells via regulation of proliferation, apoptosis and ECM degradation in chondrocytes." (PMID 37779916, 2023). "LncRNA PVT1 and GAS5 (growth arrest specific 5) regulated each other to govern chondrocyte apoptosis in osteoarthritis." (PMID 37779916, 2023). "Furthermore, this study revealed a negative correlation between miR-93-5p levels and PVT1 expression in osteoarthritis patients’ serum." (PMID 40636390, 2025).
end-stage renal disease (12 papers, 2011 to 2025). "PVT1 (plasmacytoma variant translocation 1) has been identified as a candidate gene for end-stage renal disease in T2DM." (PMID 39335472, 2024). "Plasmacytoma variant translocation 1 (PVT1) was the first gene identified as a candidate for end-stage renal disease in type 2 diabetes." (PMID 37108143, 2023). "Another lncRNA-related gene, plasmacytoma variant translocation 1 (PVT1), was classified as a candidate gene for end-stage renal disease (ESRD) in type 2 diabetes and was later found to be associated with ESRD in type 1 diabetes as well." (PMID 30909482, 2019). "Interestingly, end-stage renal disease occurring in patients with diabetes type 2 has been associated with PVT1, while variants in the same gene were associated with ESKD in patients with type 1 diabetes." (PMID 22319602, 2012). "In cardiorenal syndrome, PVT1 dysregulation relates to chronic kidney disease progression in patients with congestive heart failure, and functional data suggest that its modulation contributes to worsening renal injury." (PMID 41303683, 2025). "Recent findings indicate that denervation, immobilization, cancer cachexia, chronic kidney disease, fasting, and aging affect the expression of Pvt1, lncMUMA, Atrolnc-1, and MAR1 lncRNAs in the skeletal muscles." (PMID 32120896, 2020). "We previously observed association between variants in the plasmacytoma variant translocation 1 gene (PVT1) and end-stage renal disease (ESRD) attributed to both type 1 and type 2 diabetes, and demonstrated PVT1 expression in a variety of renal cell types." (PMID 21526116, 2011).
leukemia (12 papers, 2015 to 2024). A malignant (clonal) hematologic disorder, involving hematopoietic stem cells and characterized by the presence of primitive or atypical myeloid or lymphoid cells in the bone marrow and the blood. "LncRNA plasmacytoma variant translocation 1 (PVT1) was initially identified as a common retroviral integration site in mice with leukemia (Webb, Adams & Cory, 1984-1985)." (PMID 37744231, 2023). "Astonishingly, the 5′PVT1/3′CCDC26 chimera was the only fusion detected in a panel of 23 leukemia cell lines." (PMID 38292185, 2024). "Our research has also found other shared PVT1 fusions; for instance, in leukemia, 26 gene fusions involving the lncRNA PVT1 were detected, and surprisingly, 15 of them with PVT1 as a 5′ partner shared the same breakpoint position." (PMID 38292185, 2024). "Instead, MYC expression is at least partially under the control of the newly formed enhancer within the PVT1 locus in BETi-resistant leukemia." (PMID 32029739, 2020). "THZ1 suppresses MYC expression by perturbing the RNAPII activity at the newly formed PVT1 enhancer in BETi-resistant leukemia cells." (PMID 32029739, 2020). "Using both human and mouse BETi-sensitive or BETi-resistant leukemia cells, we identified a BETi-resistance specific enhancer within the PVT1 locus, which facilitated MYC expression in BETi-resistant cells." (PMID 32029739, 2020). "Consistently with the results obtained in APL, in the murine MLL-AF9/NRASG12D and MLL-ENL AML models, PVT1 depletion activated a myeloid differentiation program, with downregulation of cKit and leukemia stem cell signatures and upregulation of CD11b." (PMID 32228602, 2020). "When we examined the expression of these three lncRNAs, we observed that both Pvt1 and Lilam were highly upregulated in leukemia cells (RN2) as compared to their most similar normal progenitors, GMPs, or HSCs." (PMID 28875933, 2017). "Because ATRA treatment leads to a proliferation block and the differentiation of leukemia blasts, we next investigated PVT1 expression in the APL cell line NB4 before and after ATRA treatment (1 μM)." (PMID 26545364, 2015). "PVT1-NSMCE2: In leukemia cells with double minute chromosomes, which are small fragments of extrachromosomal DNA present in many human tumors, three fusion transcripts of PVT1 and the protein-coding gene NSMCE2 were identified in AML patients and cell lines of similar origin." (PMID 38919532, 2024). "In conclusion, PVT1, as an oncogene, plays an important role in the development of leukemia and may be a therapeutic target in the future." (PMID 36195846, 2022). "LncRNA PVT1 is reported to be a common retrovirus integration site in mouse leukemia." (PMID 32960485, 2021). "However, the function of PVT1 intragenic enhancers in BETi-resistant leukemia cells remains largely unexplored." (PMID 32029739, 2020). "Gene Set Enrichment Analysis (GSEA) showed an enrichment for Macrophage Differentiation genes (Ingenuity Pathway Analysis list) upon knockdown of lnc_071255 (already annotated as Pvt1), lnc_104449, or lnc_177417, while leukemia stem cell signatures showed enrichment in the control knockdown." (PMID 28875933, 2017). "Expression of lncRNAs Pvt1 and Lilam is highly induced in the leukemia context and they could, on the other hand, be dispensable for normal myelogenesis." (PMID 28875933, 2017). "Our results suggest a more general role in hematopoiesis for Pilna, while lncRNAs that show leukemia-enriched expression, Pvt1 and Lilam, could be dispensable for myeloid differentiation." (PMID 28875933, 2017). "Previous studies have focused on the c-myc oncogene, and it remains unknown whether the lncRNA PVT1 in the same region is also involved in leukemia." (PMID 26545364, 2015). "However, in these two cancer types, we did not observe any de novo H3K27ac enrichment, suggesting that the enriched H3K27ac peak at the second intron of PVT1 might be a gained BETi-resistant enhancer specific for leukemia." (PMID 32029739, 2020).